ZFP36 (ZFP36 zinc finger CCCH-type)
Diseases named in the same sentence as ZFP36 in open-access papers (continued):
Sharing a sentence is not in itself a finding about the gene and the disease.
tumor (continued). "Zfp36, HMOX1, and ATF3 have antioxidant effects and play important roles in tumor progression." (PMID 36835629, 2023). "Novel tumor-related genes like AMIGO2, ZFP36, BTG1, and DLG5 have been identified." (PMID 38275385, 2023). "In the HPA database, NRAS, STEAP3, and ALOX5 proteins are significantly expressed in tumor tissues, but the difference in the expression of ZFP36 and GABARAPL1 proteins is not obvious." (PMID 34868262, 2021). "In addition, many RNA-binding proteins, such as ZFP36/TTP, ELAVL1/HuR, and RBM10, can regulate ferroptosis in tumor cells." (PMID 33980834, 2021). "The expression of SOCS3, JUNB, and ZFP36 is highly correlated in PCa, and through immunohistochemical analysis we found SOCS3, JUNB, and ZFP36 proteins were mainly expressed in PCa epithelial cells with a small amount in tumor stroma." (PMID 32951005, 2020). "To define whether CD8 T-cells mediate the resistance to the tumor cell challenge of Zfp36−/− mice, we depleted CD8 T-cells with CD8 depletion antibody and monitored tumor growth." (PMID 29021521, 2017). "Altogether these results suggest that ZFP36 seems to undergo a more pronounced down-regulation in metastases rather than in primary tumours compared to normal tissues." (PMID 27463018, 2016). "While knockout of ZFP36 somewhat increased antigen-independent activation in CD4 CAR-T cells and cytokine secretion, ZFP36-KO cells performed similarly to unedited mock cells in a xenograft tumor model and exhibited similar cytotoxicity, proliferation, and cytokine responses in antigen settings." (PMID 38326511, 2024). "Disruption of ZFP36 in CD4 mesoCAR-T cells cocultured with antigen-negative tumor cells led to a statistically significant, slight increase in CD25+ CD69+ population; however, this difference was notable only in one of three donors and is not a strong phenotypic difference." (PMID 38326511, 2024). "Disruption of ZFP36 did not improve tumor burden control in this model." (PMID 38326511, 2024). "Strikingly, treatment with metformin might reduce tumor growth, mainly by inducing the expression of a set of genes FOSB, EGR1, ZFP36, GPR183, ATF3, and NR4A1 which are involved in DNA-binding transcriptional activation, response to hormones and the Dcp1-Dcp2 mRNA-decapping complex." (PMID 39026155, 2024). "Moreover, scRNA-seq results identified novel tumor suppressor genes (ZFP36, BTG1, DLG5, and ZBTB16), cell apoptosis-inhibitor genes, genes with pro-tumoral functionality (C1Q in TAMs), and many cell cluster-specific genes, including tumor and stromal cell-specific marker genes." (PMID 39114291, 2024). "The most significant changes in expression between sarcomatoid-tumor FOV and nonsarcomatoid-tumor FOV occurred in CD8 T cells, including downregulation of the anti-inflammatory RNA-binding protein ZFP36 (FDR < 0.001) and downregulation of TGFBR2 (FDR < 0.001)." (PMID 39639369, 2024). "In line with a potentially more “silenced” phenotype, these nonlesional tumor cells harbored elevated levels of CXCR4, CD69, HSPA1A, ZFP36, IL7R and TXNIP when compared to matched lesional skin." (PMID 34583709, 2021). "Furthermore, lower ZFP36 protein level and higher protein levels of LRP5, β-catenin, NANOG were observed in 5 tumor tissues rather than adjacent normal tissues." (PMID 40038255, 2025). "ZFP36 KO did not alter antigen-induced CD25 and CD69 expression in CD4 or CD8 mesoCAR-T cells, nor did it change the percentage of CD25+ CD69+ cells without tumor cells." (PMID 38326511, 2024). "However, unlike Zfp36, HMOX1 has a dual role in tumor cells." (PMID 36835629, 2023). "However, the role of ZFP36 and XBP1 in tumor angiogenesis has not yet been reported." (PMID 36246978, 2022). "Moreover, ZFP36, but not ZFP36L1, was shown to function as a tumour suppressor in the Eμ-Myc model." (PMID 25014217, 2014).
cancer (49 papers, 2013 to 2026). A tumor composed of atypical neoplastic, often pleomorphic cells that invade other tissues. "Recently, it was shown that components of the AP-1 transcription factor (FOS, FOSB, JUN), EGR1, and NR4A1 behave as a conserved co-regulated group of genes whose expression is associated with ZFP36 in cancer cells." (PMID 39026155, 2024). "Due to the fact that ZFP36 targets genes involved in tumorigenesis and progression, its downregulation in human cancer is associated with poor prognosis." (PMID 38351596, 2024). "ZFP36, as an RNA-binding protein, is a prominent inflammatory regulator linked to cancer and the autoimmunity process." (PMID 36685851, 2022). "TTP, also known as zinc finger protein 36 homolog (ZFP36), has been implicated with important functions in inflammation regulation, cancer development, and recently also in infection." (PMID 35573800, 2022). "PLK1 inhibition caused accelerated mRNA decay in cancer cells and was associated with reduced phosphorylation and stability of the mRNA decay‐promoting protein, tristetraprolin (ZFP36/TTP)." (PMID 33411958, 2021). "Because ZFP36/TTP is deficient in cancer—both as abundance and activity-consequent increased mRNA stability and translation of AU-rich mRNA of many cancer genes are found, contributing to hallmarks of cancer." (PMID 34535639, 2021). "ZFP36 RBPs are prominent inflammatory regulators linked to autoimmunity and cancer, but functions in adaptive immunity are less clear." (PMID 29848443, 2018). "The inverse trend between Wnt/β-catenin and ZFP36 is surely noteworthy and deserves wider studies that would help clarifying the mechanisms underlying the loss of ZFP36 in specific cancers." (PMID 27463018, 2016). "A recent report demonstrated that Etoposide induces ZFP36 expression and, moreover, it is interesting to note that ZFP36 levels rise in response to the “breast cancer susceptibility protein” BRCA1, which is implicated in the DNA damage response." (PMID 25939870, 2015). "Targets bound and negatively regulated by ZFP36 include transcripts encoding proteins necessary for immune function and cancer, and transcripts encoding other RBPs." (PMID 24401661, 2014). "Additionally, alterations such as the loss of Zfp36 further contribute to aggressive cancer phenotypes by enhancing the proliferative and invasive capabilities of cancer cells." (PMID 39853587, 2026). "ZFP36 interacted with mRNAs encoding proteins important for the immune response and cancer." (PMID 24401661, 2014). "Furthermore, the TTP-encoding gene, ZFP36, is also characterized as a cancer suppressor gene." (PMID 31046669, 2019). "Collectively, these results demonstrate that the elevation in ZFP36 caused by butyrate destabilizes LRP5 mRNA to suppress β-catenin activation, thereby suppressing cancer stem-like traits." (PMID 40038255, 2025). "Although iCAFs are often found in close proximity to cancer cells and engage in active stromal–immune crosstalk, ZFP36 and THBS1 were predominantly enriched in proCAFs." (PMID 41194113, 2025). "In contrast, silencing of ZFP36 significantly rescues butyrate-restricted Wnt/β-catenin signaling and cancer stemness." (PMID 40038255, 2025). "Upon hypoxia exposure, SERPINE1 is significantly up-regulated, while ZFP36 is down-regulated in GC cells, which is consistent with previous studies to demonstrate that hypoxia promotes the aberrant expression of SERPINE1 and ZFP36 in cancer cells." (PMID 39165353, 2024). "To summarize, low expression of ZFP36 protein under persistent P. gingivalis infection enhances the cancer‐related biological behaviour of HIOECs." (PMID 38351596, 2024). "Reduced expression of ZFP36 therefore alleviated the inhibition of cancer‐related biological processes, including proliferation, cell cycle regulation, apoptosis, migration and invasion, which consequently improved the tumorigenic potential of HIOECs." (PMID 38351596, 2024).
cancer (continued). "First, the ZFP36 relative expression was measured by RT-qPCR in both cancer cell lines using a treatment of 20 mM of metformin for 24 h." (PMID 39026155, 2024). "The mechanism investigation demonstrated the potential role of ZFP36 in regulating the cancer‐related biological behaviour of HIOECs." (PMID 38351596, 2024). "In cancer, the change of ZFP36, such as expression levels, compartment localization and activity, will result in the overexpression of cancer ARE genes." (PMID 37587140, 2023). "The 55 molecular targets belong to several important pathways, whose expression is affected by the plant toxin gossypol in cancer cells and macrophages or regulated by ZFP36/TTP in tumor cells and macrophages, as well as cinnamon polyphenol extract." (PMID 37705049, 2023). "Of note, AREG, ATF3, DUSP1, and ZFP36 were all related to cancers or pathways in cancer, and numerous studies have reported a role for these genes in different tumors." (PMID 35372438, 2022). "ZFP36, also known as adenosine triphosphate, is an RNA-binding protein (RBP) that is associated with cancer and has lower expression in some tumors." (PMID 35111153, 2021). "In our study, PLK1 was found to impart aberrant post‐transcriptional regulation of cancer‐associated ARE‐coding genes that are associated with increased abundance and stability of ZFP36/TTP, likely due to increased phosphorylation." (PMID 33411958, 2021). "In cancer cells, ZFP36 is believed to act as an EMT suppressor by binding to AU-rich elements in the mRNA 3′UTRs of Twist1 and Snail1." (PMID 34238924, 2021). "Previous studies have shown that one particular RNA-binding protein, called ZFP36, controls the translation of proteins that are important for how the immune system recognizes the body’s own tissue and deals with cancer cells." (PMID 29848443, 2018). "Particularly, it has been very recently demonstrated that ZFP36 is capable of inducing a shift from mesenchymal to epithelial phenotype in different cancer cell lines through the down-regulation of TWIST1 and SNAIL1." (PMID 27463018, 2016). "While zfp36 proteins have previously been reported to be involved in inflammatory disease and cancer, our study establishes an additional critical role during kidney development and morphogenesis." (PMID 23342169, 2013). "Furthermore, we uncover a novel mechanism of butyrate attenuating cancer stemness by accelerating LRP5 mRNA decay via ZFP36." (PMID 40038255, 2025). "ZFP36 RNA-binding proteins (RBPs) are important immunomodulators related to cancer, playing a major role in inhibiting T cell expansion and effector function, which can be leveraged as a strategy for cancer immunotherapy." (PMID 38388534, 2024). "Pfkfb3 mRNA contains a destabilising ARE61 that is bound by ZFP36 in human cancer cells." (PMID 36385275, 2022). "Moreover, we illustrated downstream‐targeted genes of JUN, FOS, FOSB, EGR1, and ZFP36 and demonstrated that these targeted genes were involved in “positive regulation of cell death”, “pathways in cancer”, “PI3K‐Akt signaling pathway”, and so on." (PMID 35037412, 2022). "Combined with findings from our current study, we speculate that AREG, ATF3, DUSP1, and ZFP36 may serve as a bridge between cancer and OSA." (PMID 35372438, 2022). "Thus, PLK1 inhibition normalized aberrant ZFP36/TTP activity in cancer cells, making PLK1‐mediated post‐transcriptional pathway and ZFP36/TTP phosphorylation promising targets for cancer therapy." (PMID 33411958, 2021). "Many studies in human cancers have also reported that ZFP36 is underexpressed in different cancers." (PMID 35008519, 2021). "Moreover, GSEA revealed that AREG, ATF3, ZFP36, and DUSP1 may regulate OSA via inflammation and contribute to OSA-related cancer risk." (PMID 35372438, 2022). "All the other genes (ATF3, EMP1, GADD45B, SOCS3, and ZFP36), distinct from EGR3, have been independently demonstrated to function as migration inhibitors in cancer cells." (PMID 38543002, 2024).
cancer (continued). "When grouped by ZNF536 expression, we found that in the cancer epithelium, ZNF536 exhibited co-expression with PHOX2B and AR, while being excluded from IFI27, IFI6, and ZFP36." (PMID 38720348, 2024). "In particular, MK2 is a master regulator for ZFP36/TTP phosphorylation in inflammation and cancer (reviewed in:)." (PMID 34535639, 2021). "As in PC3, most noteworthy genes positively correlated with this principal component are ZFP36 and DUSP1, both are known for their function of regulation in cancer progression." (PMID 32231683, 2020). "Notably, D_FB1 displays elevated levels of other cancer‐ and inflammation‐related genes—such as DNAJB1, ZFP36, JUND, TNFAIP3 and IL6—further underscoring a microenvironment characterised by heightened cellular stress and chronic inflammation." (PMID 41055332, 2026). "Increased ZFP36 further binding to AU-rich elements in 3’-untranslational region of LRP5 transcript to accelerate the mRNA decay of LRP5, thereby suppressing the activation of Wnt/β-catenin signaling-mediated enhancement of cancer stem-like traits." (PMID 40038255, 2025). "In brief, DUSP1, ZFP36, SLC2A3, HMGB1, STAT3, MT3, and ALOX5 were all FRGs that might be involved in cancer development and immune regulation." (PMID 36131791, 2022). "G144 GNS express both ZFP36 and RIP1 when cultured in proliferation medium, and we detected a reduction in the total RIP1 levels upon depletion of ZFP36, thus demonstrating that ZFP36 controls RIP1 stability in this cancer stem cell context." (PMID 25939870, 2015). "Finally, to obtain further insights into potentially relevant mechanisms in OSA pathogenesis, we used GSEA to analyze the signaling pathways related to AREG, ATF3, ZFP36, and DUSP1, and found that all four markers were related to inflammation and cancer-related pathways." (PMID 35372438, 2022).
infection (21 papers, 2014 to 2025). The state of being infected such as from the introduction of a foreign agent such as serum, vaccine, antigenic substance or organism. "We optimized adeno-Cre multiplicity of infection (MOI) based on loss of Zfp36, Zfp36l1, and Zfp36l2 mRNA expression and confirmed loss of ZFP36 and ZFP36L1 protein expression in the adeno-Cre-infected, FBS-stimulated Zfp36/l1/l2 triple-floxed MEFs." (PMID 37086408, 2023). "Interestingly, the gene encoding ZFP36 was predicted to be inhibited even though it was measured as upregulated in epithelial cells after infection with P. aeruginosa, highlighting the importance of combining in silico prediction analyses with in vitro transcriptomic studies." (PMID 35508983, 2022). "As the progenitor subset, proCAFs are likely the first to be influenced by infection, acquiring immunomodulatory features such as ZFP36- and THBS1-mediated regulation that promote immune escape in the early stages of tumorigenesis." (PMID 41194113, 2025). "This prompted us to test if both ZFP36 and ZFP36l1 are required for T‐cell competitiveness in response to high‐affinity antigens during infection." (PMID 38039407, 2024). "Our findings indicated that sustained infection with P. gingivalis inhibited the expression of ZFP36 protein and induced changes in the biological behaviour of HIOECs." (PMID 38351596, 2024). "Ten weeks after re-constitution, pre-infection baseline measurements showed a significantly greater expansion of Zfp36 KO T cells versus WT in blood." (PMID 29848443, 2018). "The gene expression of ZFP36 was significantly upregulated in the in vitro M cells and Caco-2 cells after both WT S. Typhimurium and ΔspeG infection according to both qRT-PCR and microarray analyses." (PMID 27064787, 2016). "Infection with P. aeruginosa upregulates several IEGs such as JUN, KLF2, and ZFP36 in epithelial cells." (PMID 35508983, 2022). "Our RNA-seq analysis shows that several inhibitors of the NF-kB and MAPK signaling pathways were significantly down-regulated 36 days after infection, including NFKBID, NFKBIZ, DUSP-1, -2, NR4A2, and tristetraprolin (TTP or ZFP36)." (PMID 33324683, 2020). "Lenti-miRZip-128a infection decreased the levels of mature miR-128a and significantly enhanced the expression of Lin28A, EGR2, ZFP36 and ANXA1." (PMID 28569789, 2017). "Changes in mesothelial cell gene expression of CCL5, TLR4, TNF, ZFP36, EDN1 and ITLN1 1 hour after infection with S. epidermidis." (PMID 28542390, 2017). "Using macrophage cell lines and primary alveolar macrophages we demonstrated that, like ZFP36, ZFP36L1 is prominently induced by infection." (PMID 25299049, 2014). "We conclude that the absence of ZFP36 and ZFP36L1 in T cells does not promote immunopathology, but rather increases resilience following infection with a pathogenic virus." (PMID 35477960, 2022). "Of note, measurements of ZFP36 mRNA 3 hours after infection were no longer different between the groups." (PMID 25299049, 2014). "Similar to the in vitro results, ZFP36L1 and ZFP36 expression was induced by E. coli, although induction was highest 6 hours post infection (Data not shown)." (PMID 25299049, 2014). "To determine whether ZFP36/ZFP36L1 were limiting factors for cytotoxic CD4+ T cells in vivo, we infected Zfp36fl/fl/Zfp36l1fl/flCd4cre mice with influenza A virus (PR8 H1N1) and measured CD4+ T cells in the lung 10 days following infection." (PMID 36385275, 2022). "Because myeloid-deficient ZFP36 mice exhibit a prominent spontaneous inflammatory disorder, we first investigated ZFP36L1 mutant mice in the absence of infection to determine whether they have heightened levels of inflammation at baseline." (PMID 25299049, 2014). "Interestingly, MKN-28 cells infected with ΔhtrA at both 2-h and 6-h time points exhibited increased TNF expression implying that HtrA may be involved in TNF signaling, a view that was supported by the observed deregulation of ZFP36, BCL3 and TNF during infection with the ΔhtrA mutant." (PMID 37193047, 2022).
infection (continued). "Unlike ZFP36 expression, ZFP36L1 levels are maximal under normal conditions and reduced during an infection time course." (PMID 25299049, 2014).
adenocarcinoma (3 papers, 2024 to 2025). A common cancer characterized by the presence of malignant glandular cells. "Previously published gene expression data from mouse and human PCa samples revealed that ZFP36 is significantly downregulated in phenotypic plastic/NEPC compared to adenocarcinoma samples." (PMID 40832297, 2025). "In parallel, PB-Cre4 Zfp36+/f (Zfp36+/f) and PB-Cre4 Zfp36f/f (Zfp36f/f) mice developed PIN but did not progress to adenocarcinoma." (PMID 39560993, 2024).
bacterial infection (3 papers, 2016 to 2022). "Several genes identified through our experimental approach have been linked to roles in host responses to bacterial infection (CCL5, ITLN1), immune modulation (ZFP36, NFKBIA) and damage (EDN1) during PD or during episodes of PD peritonitis." (PMID 28542390, 2017). "Thus, in model viral and bacterial infections, Zfp36 and Zfp36l1 function within CD8+ T cells to delay the onset of differentiation and limit the magnitude of acquired effector functions." (PMID 35477960, 2022). "The ZFP36 gene might be an important host defense factor of human intestinal epithelial cells, including M cells, during bacterial infection, and requires further study for elucidation." (PMID 27064787, 2016).
Cardiovascular Diseases (3 papers, 2017 to 2023). "Following a literature review, we chose four RBPs (HSPA1A, ZFP36, TRIM21, and P2RX7) that play important roles in the development of cardiovascular diseases for further co-expression analysis." (PMID 37180137, 2023).
kidney disease (1 paper, 2013). "Given the conservation in gene structure and function between the amphibian and mammalian proteins and the conserved mechanisms for pronephros development our studies have uncovered a potential role of zfp36 gene in human kidney disease that merits further investigation." (PMID 23342169, 2013).